C1orf56 (chromosome 1 open reading frame 56)
Description:
Involved in control of cellular proliferation. Onconcogenic modifier contributing to the tumor suppressor function of DNMT3B.
Synonyms: MENT; FLJ20519
Tractability: Antibody: UniProt places it where antibodies can reach, with high confidence; UniProt predicts a signal peptide or a membrane-spanning region; its Gene Ontology location is reachable by antibodies, with medium confidence.
Gene: Protein-coding gene on chromosome 1 (151,047,751 to 151,051,986, forward strand). Ensembl gene ENSG00000143443.
Subcellular location: Secreted
Gene Ontology:
Molecular function: protein binding
Biological process: regulation of cell population proliferation
Cellular component: extracellular region
Genetic constraint (gnomAD): Loss-of-function variants: 14 observed, 21.77 expected, observed/expected ratio (o/e) 0.64, 90% interval 0.42 to 1. The upper end of that interval is the gene's LOEUF score, 1, which puts it in group 4 of 6, group 1 being the genes least tolerant of losing a copy. Missense variants: 424 observed, 470.9 expected, observed/expected ratio (o/e) 0.9, 90% interval 0.83 to 0.98. Synonymous variants: 187 observed, 203.29 expected, observed/expected ratio (o/e) 0.92, 90% interval 0.82 to 1.04.
Homologues: Orthologues: chimpanzee C1H1orf56 (99% identical), macaque C1H1orf56 (94% identical), rabbit C1orf56 (71% identical), pig C1orf56 (68% identical), rat C2h1orf56 (65% identical), mouse Gm128 (64% identical), dog C1orf56 (63% identical), guinea pig C1orf56 (63% identical).
Diseases named in the same sentence as C1orf56 in open-access papers:
C1orf56 is named in the same sentence as 5 diseases in open-access papers, as found by Europe PMC text mining. Sharing a sentence is not in itself a finding about the gene and the disease. The quoted sentences say what the papers report.
lymphoma (2 papers, 2017 to 2025). A malignant (clonal) proliferation of B- lymphocytes or T- lymphocytes which involves the lymph nodes, bone marrow and/or extranodal sites. "C1orf56 has also been implicated in the development of lymphomas in murine models and is also overexpressed in many human lymphomas." (PMID 40352330, 2025).
myeloma (1 paper, 2024). "The results suggest that three genes, CRIP1, HIST1H1C and RNF125, are significantly overexpressed in myeloma cell lines and may contribute to the poor prognosis in malignant plasma cell samples, whereas C1orf56 and S100A6 may contribute to the poor prognosis in microenvironmental cell samples." (PMID 38278930, 2024).
infection (1 paper, 2021). The state of being infected such as from the introduction of a foreign agent such as serum, vaccine, antigenic substance or organism. "Finally, in cluster 6 cells, only C1orf56 was significantly expressed in the infection group (log2FC > 1.0), and no genes specifically expressed in the cluster were found." (PMID 34214113, 2021).
C1orf56 also shares sentences with these, for which no sentence is quoted: cancer (1 paper); tumor (1).